INHA (inhibin subunit alpha)
Diseases named in the same sentence as INHA in open-access papers (continued):
Sharing a sentence is not in itself a finding about the gene and the disease.
endophthalmitis (1 paper, 2019). An infectious process affecting the internal structures of the eye. "B. cereus endophthalmitis is a devastating eye infection that causes blindness due to the release of a variety of extracellular tissue-destructive exotoxins, including phosphatidylinositol-specific phospholipase Cs (PI-PLCs), immune inhibitor A metallopeptidase (InhA), and hemolysin BL (HBL)." (PMID 31796569, 2019). "Taken together, the acquisition of plcA-2, InhA-3, InhA-4, hblA-5, and fliD suggests that escaping host immune responses, particularly from macrophages, increases virulence and may be central to the ability of intraocular strains to cause devastating endophthalmitis." (PMID 31796569, 2019).
germ cell tumor (1 paper, 2024). A benign or malignant, gonadal or extragonadal neoplasm that originates from germ cells. "Thus, epithelial ovarian tumors express cytokeratins (CK), germ cell tumors placental alkaline phosphatase (PLAP), and SCSTs inhibin-alpha (INHA), a peptide hormone produced by ovarian cells to inhibit follicle-stimulating hormone (FSH)." (PMID 38998048, 2024).
granular cell tumor (1 paper, 2022). An unusual benign or malignant neoplasm characterized by the presence of neoplastic large polygonal cells with granular, eosinophilic cytoplasm which contains abundant lysosomes. "INHA protein expression is generally considered an important diagnostic feature for adrenocortical tumors and granular cell tumors, as well as sex cord stromal tumors of the testis and the ovary." (PMID 36289769, 2022). "Our data corroborate that INHA is commonly expressed in various types of sex cord stromal tumors and granular cell tumors, as well as adrenal cortical neoplasms." (PMID 36289769, 2022).
Infertility (1 paper, 2022). "In conclusion, the clinical and molecular characteristics of these two patients suggest that homozygous INHA mutations cause decreased prenatal and postnatal testosterone production and infertility in males." (PMID 35235537, 2022). "Homozygosity for INHA mutations causes decreased prenatal and postnatal testosterone production and infertility in males, while the heterozygous female and male carriers of INHA mutations do not have any abnormality in sex development and reproduction." (PMID 35235537, 2022).
kidney cancer (1 paper, 2021). Primary or metastatic malignant neoplasm involving the kidney. "In kidney cancers, INHA was a negative predictor of survival in both renal clear cell and renal papillary cell carcinoma, consistent with prior findings." (PMID 33819300, 2021).
nasopharyngeal carcinoma (1 paper, 2024). A carcinoma arising from the nasopharyngeal epithelium. "The levels of INHA and INHBB in nasopharyngeal cancer patients were lower than those in healthy people, and the levels in stage III + IV patients were lower than those in stage I + II patients." (PMID 38847724, 2024).
ovarian diseases (1 paper, 2024). "Conversely, several downregulated genes crucial for folliculogenesis were also found to be linked to ovarian diseases, namely, genes for sex hormone biosynthesis such as STAR, CYP17A1, and ALDH1A1, along with genes required for follicle development, such as INHA." (PMID 38126810, 2024).
trisomy 21 (1 paper, 2023). A chromosomal disorder consisting of the presence of an extra chromosome 21. "Accordingly, we aim to unravel the physiology of these markers (PAPP-A, free hCGβ, hCG, AFP, uE3, inhA, and cell-free feto–placental DNA) and their regulation, focusing on the placenta and try to explain their abnormal variations in maternal serum in trisomy 21-affected pregnancies." (PMID 37108840, 2023).
tumor (18 papers, 2010 to 2025). "Loss of INHA expression has been detected in only a small subgroup of human ACCs, pleading against a significant tumor suppressor role of INHA in human adrenocortical carcinogenesis." (PMID 25111790, 2014). "Our findings that INHA is significantly associated with survival in sixteen of the twenty cancers analyzed, correlating positively with survival in five cancers and negatively in ten, highlight INHA’s differential role as a tumor suppressor or promoter depending on the specific cancer type." (PMID 33819300, 2021). "In regions of tumor-iNHA cell interactions, we also detected CLSTN1 accumulations, indicating that CLSTN1 is localized to both homotypic and heterotypic cell interactions." (PMID 39762313, 2025). "The same tissue and tumor type are seen with the Cys291Trp in the ligand of INHA that shares β8Cys@1 and β8Cys@4 with TGFB2." (PMID 36214621, 2022). "Inhibins are early tumor suppressors, as the INHA-/- mice form spontaneous gonadal and granulosa cell tumors." (PMID 33819300, 2021). "Earlier, inhibin alpha-subunit (INHA) was found to have a tumor suppressive role in adrenocortical tumorigenesis." (PMID 32414074, 2020). "The possible mechanism was that INHA was involved in tumor angiogenesis, leading to tumor metastasis and poor prognosis." (PMID 33072571, 2020). "Immunohistochemical study showed high INHA expression in the tumor, suggesting SCST." (PMID 38998048, 2024). "We next evaluated if INHA expression was elevated in vivo with increasing xenograft tumor size." (PMID 35654828, 2022). "INHA expression was also significantly correlated with tumor size." (PMID 35654828, 2022). "In mammals and teleosts, inhibin α (INHA/Inha) has been reported to function as a tumor suppressor." (PMID 36469526, 2022). "The evidence for INHA as a tumor suppressor in human ACC is conflicting." (PMID 25111790, 2014). "The tumor harbouring the S184F change expressed a normal level of INHA mRNA, but function or protein degradation could still be affected by the introduction of the benzyl side ring." (PMID 25111790, 2014). "The lower frequency of this SNP in ACC samples appears to contradict the hypothesis that INHA is a tumor suppressor in human ACC." (PMID 25111790, 2014). "However, here the increase in INHA levels in endothelial cells in response to hypoxia was only moderate as compared to in tumor cells suggesting a potential competition in the tumor microenvironment between activin and inhibin." (PMID 35654828, 2022). "Insights into the regulatory control of INHA expression could shed further light on the role of INHA in human adrenal tumorigenesis and on the variability of serum free circulating inhibin levels that could function as serum tumor marker in ACC patients." (PMID 25111790, 2014). "CLSTN1 accumulation was particularly evident in contacts between tumor cells and iNHA after P/12k treatment, where it focally accumulated specifically in contacts between UW228 and iNHA." (PMID 39762313, 2025). "Tumor nodules in TGFBR1CA; RosamTmG; Amh-Cre mice were also positively stained for FOXL2 and INHA, consistent with the development of TGCTs." (PMID 38067144, 2023). "Several reports using genetically modified mouse models highlight the importance of TGFB superfamily signaling components, such as INHA, SMAD3, SMAD1/5, and BMPR1A/BMPR1B, in sex cord-stromal tumor development." (PMID 29221447, 2017). "In man, INHA expression varies widely within ACC tissues and its circulating peptide inhibin pro-αC has been described as a novel tumor marker for ACC." (PMID 25111790, 2014). "Also, we identified novel predicted tumor-suppressive ligands (SLIT3, DCN, CCN3, THBS1, INHA and INHBA), proteins (DNASE1L3, SULF1, PTEN, OAS1, and DAB2IP), and receptors (P2RX4, CDHR2, PTPRJ, and PTPRH) in MSC1 cells." (PMID 40564222, 2025).
tumor (continued). "In this study, we have found an association between the expression of the follow proteins (STAT5, STAT3_pS727, BMP6, CD74, TFRC, INHA, and STAT5_pY694) involved in iron homeostasis and the type of tumor tissue (breast cancerous vs. non-cancerous)." (PMID 28216608, 2017). "Moreover, tumors from TGFBR1-CACcre ovaries were highly proliferative, expressed granulosa cell markers FOXL2 and INHA, and were immunoreactive for KRT8 during tumor progression." (PMID 27344183, 2016). "Double immunofluorescence revealed low expression or absence of INHA in KRT8-positive cells within tumor lobules, suggesting distinct identity of KRT-positive cells." (PMID 27344183, 2016). "This is consistent with the apparent lack of expression of INHA in the normal and tumor tissues of all three patients and implicates INHBA as a potential oncogene in OSCC." (PMID 20174472, 2010). "Also, mRNA levels of INHA in ACCs were not related to tumor characteristics (data not shown)." (PMID 25111790, 2014). "Although few immune-related genes had a high expression in cold tumor, such as MMP8, most genes highly express in cold tumor are not so closely related to immune responses, including CGA, INHA, IBSP, and CHRNA9." (PMID 33816503, 2021).
cancer (16 papers, 2009 to 2025). A tumor composed of atypical neoplastic, often pleomorphic cells that invade other tissues. "Tumor-targeting therapies involve the use of Salmonella carrying specific RNA, such as short hairpin RNA (shRNA) against inhibin alpha subunit (INHA) for treating late-stage cancers." (PMID 38543481, 2024). "Inhibinα levels are also predictive of survival in multiple cancer types with gene signatures that correlate with INHA expression, providing a highly accurate prognostic model for predicting patient outcomes." (PMID 35654828, 2022). "Based on the potential role of inhibins’ in cancer angiogenesis, we tested the impact of hypoxia, a key regulator of angiogenesis, on INHA expression." (PMID 35654828, 2022). "Our findings provide significant new information on the specific cancers impacted by the genes investigated here, INHA, INHBA, INHBB, ENG and TGFFBR3, and shed light on potential functional dependencies." (PMID 33819300, 2021). "The heterodimeric TGF-β family ligand Inhibin (INHA) is a novel paracrine factor involved in cancer angiogenesis and metastasis." (PMID 34924998, 2021). "INHA’s dependency on each coreceptor examined in survival analysis revealed distinct signatures between different cancer types." (PMID 33819300, 2021). "INHA is also involved in cancer invasion and metastasis in various types of cancer." (PMID 36455876, 2022). "Because the proposed cellular site for pro-tumourigenic and pro-metastatic action of INHα is cancer epithelial cells, we over-expressed INHA in metastatic epithelial PCa cell lines, LNCaP and PC3, to evaluate functionally the effect of elevated levels of INHα in PCa." (PMID 19436293, 2009). "Thus, the INHA-TGFBR3-ENG signature has pan-cancer prognostic value." (PMID 33819300, 2021). "INHA and INHBA, inhibit activin signaling by competing for activin receptor binding, thereby reducing proliferation in cancer cells." (PMID 40564222, 2025). "Clustering analysis for genes correlated with INHA, TGFBR3, or ENG in cancers revealed ENG and TGFBR3 had very few genes correlated exclusively to one or the other." (PMID 33819300, 2021). "Additional gene signature analysis reveals that INHA, along with one of its main receptors (i.e., TGBFR3) faithfully predicts patient outcomes in a wide spectrum of cancer types." (PMID 33819300, 2021). "Gene signatures from our analysis reveal robust relationships between INHA, ENG, and TGFBR3 and other established cancer biomarkers." (PMID 33819300, 2021). "The morphogenetic BMP signaling (BMP6 and INHA), the pro-inflammatory JAK/STAT pathway and CD74, a pro-inflammatory component in terms of infiltrating macrophages, resulted in discriminating between cancer and non-cancer samples." (PMID 28216608, 2017). "Furthermore, in parallel experiments, ImmTAB-inhA molecules did not induce IFN-γ secretion by PBMC in response to a panel of inhA antigen negative cancer cell lines expressing various levels of HLA-E and presenting different sets of endogenous HLA-E ligands." (PMID 38691588, 2024). "Moreover, INHA itself was dependent on TGFBR3 and ENG/CD105 in multiple cancer types." (PMID 33819300, 2021). "We found INHA to only be a negative predictor of survival in patients expressing low ENG indicating INHA might act independent of either coreceptor in these cancer types." (PMID 33819300, 2021).
infection (7 papers, 2011 to 2024). The state of being infected such as from the introduction of a foreign agent such as serum, vaccine, antigenic substance or organism. "Identifying the prevalence of katG and inhA mutations gives insight into potential treatment options that can be used for individuals with DR-TB disease and presumed sub-clinical infection." (PMID 31425565, 2019). "And also our test on the mutations of the putative INH-target genes, katG, inhA, and ahpC further confirmed one patient (number 18) with mixed infection by the heterogeneous genotypes." (PMID 26064938, 2015). "On the other hand, InhA was previously implicated in the survival of germinating spores within host macrophages at the early stage of infection." (PMID 21437287, 2011). "Inactivation of BPL resembles inhibition of InhA, the target of isoniazid, in that blocking both of these Mtb enzymes interferes with cell envelope biosynthesis and kills growing Mtb rapidly both in vitro and during in vivo infection." (PMID 29695454, 2018).
gastrointestinal disease (1 paper, 2020). A disease that occurs in the gastrointestinal system, excluding the hepatobiliary system. "Although the virulence factors associated with clinical non-gastrointestinal diseases are unclear, in our clinically isolates, we found the contemporary presence of genes encoding to NHE, entA, entFM, sph, cerA, cerB, inhA, plcA, and plcB virulence factors, in co-presence of the PlcR." (PMID 33510722, 2020).
INHA also shares sentences with these, for which no sentence is quoted: Hypergonadotropic hypogonadism (2 papers); serous ovarian cancer (2); cholangiocarcinoma (1); Cirrhosis (1); clear cell carcinoma (1); colorectal adenocarcinoma (1); endometrial stromal sarcoma (1); endometriosis (1); gastric adenocarcinoma (1); glioblastoma (1); glioma (1); hyperandrogenism (1); hypogonadism (1); infectious disease (1); intestinal inflammation (1); leiomyosarcoma (1); lymph node metastasis (1); Lymphatic Metastasis (1); metastatic melanoma (1); metastatic tumors (1); neuroendocrine tumors (1); neuroendocrine tumors of the pancreas (1); Obesity (1); pancreatic acinar cell carcinoma (1); pancreatic cancer (1); peripheral neuropathy (1); pregnancy hypertension (1); primary testicular failure (1); renal carcinoma (1); renal papillary cell carcinoma (1).
A further 6 diseases each share a sentence with INHA in 1 paper.